FBXL21P (F-box and leucine rich repeat protein 21, pseudogene)
Description:
Substrate-recognition component of the SCF(FBXL21) E3 ubiquitin ligase complex involved in circadian rhythm function. Plays a key role in the maintenance of both the speed and the robustness of the circadian clock oscillation. The SCF(FBXL21) complex mainly acts in the cytosol and mediates ubiquitination of CRY proteins (CRY1 and CRY2), leading to CRY proteins stabilization. The SCF(FBXL21) complex counteracts the activity of the SCF(FBXL3) complex and protects CRY proteins from degradation. Involved in the hypothalamic suprachiasmatic nucleus (SCN) clock regulating temporal organization of the daily activities (By similarity).
Synonyms: FBL21; FBL3B; formerly FBXL3B; FBXL3P; FBXL21
Gene: Transcribed unitary pseudogene on chromosome 5 (135,934,368 to 135,941,671, forward strand). Ensembl gene ENSG00000164616.
Subcellular location: Cytoplasm, cytosol; Nucleus
Diseases named in the same sentence as FBXL21P in open-access papers:
FBXL21P is named in the same sentence as 4 diseases in open-access papers, as found by Europe PMC text mining. Sharing a sentence is not in itself a finding about the gene and the disease.
FBXL21P shares sentences with these, for which no sentence is quoted: Fanconi anemia (1 paper); medulloblastoma (1); muscle disorders (1); schizophrenia (1).